AQP4 (aquaporin 4)
Diseases named in the same sentence as AQP4 in open-access papers (continued):
Sharing a sentence is not in itself a finding about the gene and the disease.
neurological diseases (continued). "Thirty age-matched participants with AQP4–NMOSD, 17 participants with MOG antibody associated disease (MOGAD), and 15 participants with other neurological disorders (OND) were included as controls." (PMID 35413922, 2022). "With AQP4 as a crucial water channel facilitating fluid fluxes in the CNS, neurological disorders affecting AQP4 physiology call for further research to investigate changes in CNS fluid dynamics and the impact of astrocytic dysfunction in neuroinflammation." (PMID 34299111, 2021). "While 13 unique AQPs have been identified in the human body thus far, aquaporin-4 (AQP4) has become an interesting therapeutic target in various neurological disorders, due to its variety of functions and widespread expression in the nervous system." (PMID 32111087, 2020). "AQP4 expression and activity in various neurological disorders has been examined, and several intriguing discoveries have been made." (PMID 32111087, 2020). "With the increase in interest in AQP4 as a potential therapeutic target, and the implications AQP4 activity has on many neurological disorders, it is important to have a clear understanding of the myriad of ways in which AQP4 is known to be regulated." (PMID 32111087, 2020). "It is well known that AQP4 possess very high single channel water permeability (3-fold greater than that of AQP1), while previous studies of AQP4 mainly aim at nervous system diseases." (PMID 28265203, 2017). "Current evidence indicates that brain AQP4 is involved in various astrocytic functions related to neurological diseases, including brain fluid and ion homeostasis." (PMID 29216295, 2017). "Together, these studies suggest the effect of AQP4 deletion on astrocyte reactivity depends on the types and stages of neurological diseases." (PMID 26526066, 2015). "The purpose of this review is to address this open area of debate as it relates to the role of AQP4 channels in brain water clearance in neurological disorders." (PMID 26526878, 2015). "Seropositivity rates for NMO-IgG and AQP4 autoantibodies in different groups of central nervous system idiopathic inflammatory demyelinating disorders, other neurological disorders, and healthy subjects." (PMID 20822515, 2010). "Water channel proteins, known as aquaporins (AQPs), notably AQP-1 and AQP-4, appears to be involved in the pathophysiology of several neurological diseases." (PMID 20969805, 2010). "Autoimmune antibodies to various protein targets, such as myelin oligodendrocyte glycoprotein (MOG), major basic protein (MBP), dipeptidyl-peptidase-like protein 6 (DPPX), and aquaporin-4, have been described and are even applied in the diagnosis of certain neurological disorders." (PMID 41009363, 2025). "Therefore, future studies should incorporate objective validation with additional samples from patients with other neurological disorders to assess the accurate clinical performance of AQP4-CLEIA." (PMID 39941228, 2025). "Therefore, specific testing for AQP4-IgG is crucial in clinical practice for properly diagnosing and treating these neurological disorders." (PMID 39941228, 2025). "Firstly, AQP4 expression exhibits bidirectional changes in neurological disorders." (PMID 39295943, 2024). "jSLE patients with higher severity scores, neurological disorders, or white matter lesions could develop antibodies against AQP4." (PMID 37208665, 2023). "AQP4 is known to be involved in various astrocytic functions related to neurological disorders." (PMID 35884950, 2022). "We conclude that BMP signaling regulates AQP4 expression and microdistribution and—by inference—that perturbed BMP signaling could contribute to the mislocalization of AQP4 that has emerged as a common denominator of a range of neurological disorders." (PMID 35518645, 2022). "Aquaporin-4 water channels play a central role in brain water regulation in neurological disorders." (PMID 26526878, 2015). "AQP4 channels play important roles in neurological disorders." (PMID 26526878, 2015).
neurological diseases (continued). "Successful treatment of the underlying malignancy—whether by surgical resection, chemotherapy, or radiation—frequently leads to stabilization of the neurological disease, a reduction in relapse rates, and, in some documented cases, a decrease in or complete seroreversion of AQP4-IgG titers." (PMID 40963604, 2025). "Therefore, structural damage to the PVS and abnormal polar distribution of AQP4 may be an important cause of impaired CSF-ISF exchange, metabolic waste deposition, and ultimately the development or exacerbation of neurological diseases." (PMID 39144708, 2024). "Given the significance of AQP-4 in the pathophysiology of numerous neurological disorders and its involvement in fundamental mechanisms related to high-level functions, it is reasonable to assume that AQP-4 is also implicated in various functional impairments associated with neurological disorders." (PMID 39534317, 2024). "In addition, studies of AQP4 knockout mice have shown that AQP4 may play a pro-inflammatory role in different mouse models of neurological diseases." (PMID 35518645, 2022). "Therefore, it seemed that preserving the Aqp4 expression level might be an effective method to maintain the GS function in various neurological diseases." (PMID 33574749, 2020). "Aquaporin 4 (AQP4) is highly expressed on astrocytes and is critical for controlling brain water transport in neurological diseases." (PMID 35260880, 2022). "Thus, we suggest that 67LR-p38 MAPK/ERK1/2-PI3K-AKT-AQP4 signaling cascades may mediate serum extravasation and AQP4 expression in astroglio-vascular systems, which is one of the considerable therapeutic targets for vasogenic edema in various neurological diseases." (PMID 32664509, 2020). "Another potential biomarker is MOG-IgG which can be present in sera from AQP4-IgG seronegative NMO patients and in other neurological disorders (ADEM, paediatric MS)." (PMID 26950113, 2016). "Together, these results provide a unified physical picture of glymphatic transport in the optic nerve, yield testable predictions for how AQP4 function, PVS patency, and sleep modulate size-dependent clearance, and offer guidance for targeting impaired waste removal in neurological disease." (PMID 41295017, 2025). "Aquaporin-4 (AQP4) is the prime water channel expressed in the CNS and is primarily expressed in astrocytes, thus playing a vital role in normal brain homeostasis and various neurological diseases." (PMID 34489623, 2021). "Moreover, in some neurological disorders, i.e., MS, there is increased expression of AQP1 and AQP4 in the brain, probably due to the need to maintain water homeostasis." (PMID 26950113, 2016). "Aquaporin-4 (AQP4) is a water channel protein that links the astrocytic endfeet to the blood-brain barrier (BBB) and regulates water and potassium homeostasis in the brain, as well as the glymphatic clearance of waste products that would otherwise potentiate neurological diseases." (PMID 38077948, 2023). "Therefore, the destruction of PVS structure and the abnormal distribution of AQP4 polarity may be important reasons for the exchange disorder between CSF and ISF, the deposition of metabolic waste, and finally lead to or aggravate nervous system diseases." (PMID 35847591, 2022). "The absence of AQP4 function does not result in neurological disorder in AQP4 knockout mice." (PMID 23202933, 2012).
cancer (57 papers, 2011 to 2025). A tumor composed of atypical neoplastic, often pleomorphic cells that invade other tissues. "Like brain metastasis, the significant up-regulation of AQP4 potentially accounts for the hallmark of malignant tumors: cerebral edema." (PMID 38201663, 2024). "AQP4 expression influences the degree of CD8+ T-cell infiltration level as well as cancer-associated fibroblast infiltration in CNS tumors." (PMID 34113257, 2021). "Data mining of the gene set for the potential relevant functions and correlating diseases revealed major associations of AQP4 to cancer and respiratory disease, as well as links to biological processes like cell cycle regulation, lipid metabolism, cellular movement and cell-to-cell signalling." (PMID 21548930, 2011). "Recent evidence suggests that AQP4 expression may be linked to several diseases such as cancer." (PMID 34113257, 2021). "However, OV cancers were found to be negatively associated to AQP4 expressions." (PMID 34113257, 2021). "High-throughput T-cell receptor (TCR) and B-cell receptor (BCR) sequencing provides direct evidence of oligoclonal expansions, identifying the specific T and B cell clones that likely recognize shared AQP4 epitopes on both the cancer cells and CNS astrocytes." (PMID 40963604, 2025). "Spatial transcriptomics can map the interactions between AQP4-expressing cancer cells and immune cells, and compare that “immune synapse” to the one causing astrocyte damage in the brain." (PMID 40963604, 2025). "According to reports, it has been observed that AQP4 can separate from OAPs and disperse itself evenly throughout the whole outermost layer of cancer cells." (PMID 39247976, 2024). "As a result, AQP4 inhibitors potentially represent an immensely effective and original class of cancer therapeutics." (PMID 39247976, 2024). "Since degradation and remodeling of the extracellular matrix are essential processes for cancer cell invasion and involve degradation of agrin, it is conceivable that AQP4 localization and expression is consequently affected." (PMID 35187599, 2022). "So far, four AQPs (AQP1, AQP4, AQP5, and AQP9) have been linked to EMT in several cancer cell models." (PMID 35847914, 2022). "Following that, we examined the relationships between the AQP4 gene, immunotherapy-related prediction pathway enrichment scores, and anti-cancer immune process activity." (PMID 36523816, 2022). "Our results demonstrated that a low AQP4 membrane expression was correlated with more advanced cancer stages, meaning the presence of lymph node metastases (89% vs. 67%, p < 0.05, respectively)." (PMID 36233821, 2022). "We further analyzed the anti-cancer immune process activity differences between high and low AQP4 gene expression groups." (PMID 36523816, 2022). "Aquaporin-4 (AQP4) is in growing recognition as potential marker for cancer progression, differentiation and therapeutic intervention." (PMID 33455577, 2021). "AQP4 expressions across different types of cancer data available on the TCGA was assessed using the TIMER2 approach." (PMID 34113257, 2021). "More studies should be directed toward clarifying the precise effects of AQP4 in various human cancers." (PMID 34113257, 2021). "VEGF and IL‐6 release and aquaporin 4 (AQP4) expression were assessed as indirect markers of cancer‐related angiogenesis and cell invasion, respectively." (PMID 32022398, 2020). "Conversely, previous studies of cancer-associated NMOSD, comprising mainly case reports, postulated a paraneoplastic etiology, particularly if the tumor expresses AQP4." (PMID 28068933, 2017). "To further address this issue, we transfected a plasmid containing VSV-tagged AQP4 into three MDA-435 cancer cell lines stably expressing WT Cav1, the dominant negative Y14F form, or one bearing the Y14D phosphomimetic mutation." (PMID 29326556, 2017).
cancer (continued). "Our RT-PCR results for AQP4 mRNA entirely support these immunohistochemical analyses; we identified AQP4 mRNA in follicular cell-derived carcinoma cell lines." (PMID 22808259, 2012). "The probable involvement of AQP4 in human cancer has drawn much more attention in recent years." (PMID 39247976, 2024). "To assess the role of different sized EV in cancer cell–cell communication, we sought to determine whether AQP4 expressing cell-derived EVs affect the invasive response of receiving cells." (PMID 36071478, 2022). "Of note, at least four AQPs (AQP1, AQP3, AQP4, and AQP9) have been shown to modulate the activity of specific MMPs, which appears to be a key mechanism underlying the promotion of cellular local invasion and cancer cell metastasis by AQPs." (PMID 35847914, 2022). "Our study provides robust evidence supporting AQP4 as a new candidate for cancer treatment." (PMID 36523816, 2022). "However, a relative AQP4 protein expression was observed in the cytoplasmic membrane of cancer cells in 16% of ADC samples." (PMID 36233821, 2022). "The incorporation of AQP4 targeting is an overlooked and underdeveloped strategy in cancer therapy." (PMID 34113257, 2021). "Recent literature highlights the central role of AQP4 in cancer initiation and progression." (PMID 34113257, 2021). "Different cancers were demonstrated to have distinct profiles of AQP4 expressions." (PMID 34113257, 2021). "AQP4 has been found to play a central growth in cancer development and progression." (PMID 34113257, 2021). "AQP4 expression was noted to be significantly related to levels of cancer-associated fibroblasts of the CESC, CHOL, HNSC [HPV (Human papillomavirus) -], LIHC, STAD, TGCT and THYM cancers." (PMID 34113257, 2021). "A variety of studies suggested AQP4 involvement in promoting cancer cell migration." (PMID 34070729, 2021). "Although this resemblance served the purpose of properly separating cancer cell types, mesenchymal cancer cells lack expression of important tRG genes such as AQP4, FAM107A, SOX9, and GLI3, and tRG lack the expression of mesenchymal genes such as CD44 and TIMP1." (PMID 32641768, 2020). "We expected that the functional interaction between ATP1A3 and AQP4 might mediate the anti‐cancer effect of CS‐6 and the chemosensitizing effect of CS‐6 on TMZ." (PMID 31746080, 2020). "Because of this peculiar location, AQP4 has been suggested to be involved in different aspects of brain edema pathogenesis, probably with different effects depending on the nature of the disease (for example, cancer or traumatic damage)." (PMID 27367682, 2016). "A second kind of strategy might include use of small RNAs, complementary to specific regions of AQP4 mRNA (siRNAs): it has been reported, in fact, that down-regulation of AQP4 using this approach can induce cancer cell apoptosis." (PMID 27367682, 2016). "Among these autoantibodies, those targeting aquaporin-4 (AQP4) and myelin oligodendrocyte glycoprotein (MOG) are associated with a low risk of cancer, even though MOG or AQP4 expression may be detected on cancer tissue, supporting a paraneoplastic origin in those few reported cases." (PMID 37360349, 2023). "Furthermore, a low AQP4 membrane expression was present in 89% of ADC samples, compared to a high AQP4 expression (scores 3–9), and it was correlated with worse cancer-related characteristics with lymph nodes metastases, which was a significant difference (p = 0.046)." (PMID 36233821, 2022). "In other types of cancers, AQP3, AQP4, or AQP5 are increased in expression and influence viability, proliferation and migration." (PMID 31477744, 2019). "The downregulation of AQP4 may increase TNF-α expression in the gastric mucosa by activating the NF-κB pathway, further exacerbating inflammation and promoting cancer cell proliferation and migration." (PMID 40255569, 2025).
cancer (continued). "Overall, several AQPs, including AQP1, AQP3, AQP4, AQP5, AQP8, and AQP9, have been suggested to transport H2O2, and their expression promotes cancer cell growth and migration, However, solid data exist only for AQP3- mediated H2O2 transport as one of the key mechanisms for cancer cell migration." (PMID 35847914, 2022). "A high expression of AQP3 was significant in cancer tissue when compared to the control group (p < 0.001), whereas a low AQP4 membrane expression was noted as significantly common in cancer tissue compared to non-neoplastic lung tissue (p < 0.001)." (PMID 36233821, 2022). "Immunohistochemistry of AQP4 indicated that AQP4 protein was more highly expressed in normal breast tissues than in cancer, where AQP4 localized to the membrane and cytoplasm." (PMID 36212456, 2022). "Previous reports showed that AQP4 was poorly expressed in ADC cells and overexpression of AQP4 could inhibit the migration and invasion of cancer cells through the suppressive role of miR-196b." (PMID 36233821, 2022). "There is no consensus that AQP4‐positive NMOSD should be monitored regularly for cancer if immunological factors are excluded, but we believe that older patients with associated high‐risk factors should be monitored." (PMID 34520629, 2021). "We speculated that for AQP4‐positive NMOSD patients, especially the elderly, if other immunological factors are excluded, cancer screening should be taken under consideration that is of great significance for disease prognosis." (PMID 34520629, 2021). "AQP4 was absent in human carcinoma tissue in contrast with healthy tissue, indicating its downregulation during gastric tumorigenesis." (PMID 34721627, 2021). "Currently, the correlation between ATP1A3 and AQP4 in human cancers and their mechanistic interactions have not been addressed." (PMID 31746080, 2020). "In contrast, AQP4 was found to be absent in human carcinoma tissue in contrast with healthy tissue, indicating its downregulation during gastric tumorigenesis." (PMID 27589719, 2016). "All 14 ON patients with malignant tumors included in this study showed negative results in serum tests for pathogens and autoantibodies including antinuclear antibodies, anticardiolipin antibodies, antineutrophil cytoplasmic antibodies, AQP4-Ab and MOG-Ab." (PMID 35222744, 2022). "Unfortunately, the patient did not agree to do further colonoscopy, so we could not stain the cancer tissue for AQP4 to verify our inference." (PMID 34520629, 2021). "In addition, AQP3, AQP4 and AQP5 exhibited differential expression between human gastric carcinomas and corresponding normal tissues; AQP3 and AQP5 protein expression was detected as remarkably stronger in the human carcinoma tissues than that in normal mucosa by immunofluorescence." (PMID 27589719, 2016).